KIT (KIT proto-oncogene, receptor tyrosine kinase)
Diseases named in the same sentence as KIT in open-access papers (continued):
Sharing a sentence is not in itself a finding about the gene and the disease.
tumor (continued). "The possible drivers of tumour growth screened included KIT, TERT, and RAS family genes." (PMID 23866769, 2013). "HSP-90 promotes survival of tumor cell, induces their growth and metastasis even when there are no growth factors via continued protein translation and cellular proliferation; Its client proteins include: KIT, AKT, CDK4, telomerase, Bcl-2, MMP2 and others." (PMID 23164412, 2012). "KIT and PDGFRα genes code for their respective tyrosine kinase receptors, and known mutations result in constitutive activation driving the proliferation and survival of GIST tumor cells." (PMID 22429770, 2012). "We report here the development, validation, and clinical implementation of a multiplexed assay designed to simultaneously detect 43 recurrent mutations in BRAF, KIT, NRAS, GNA11, GNAQ, and CTNNB1 using tumor-derived DNA from formalin-fixed paraffin-embedded (FFPE) tissues." (PMID 22536370, 2012). "Toceranib also exhibited activity against multiple tumor types in the original phase 1 study, suggesting that the action of toceranib against receptors other than KIT may play a role in the responses observed in solid tumors." (PMID 22630170, 2012). "The discordant results between message and protein expression may be secondary to detection of KIT message present in mast cells and other inflammatory cells present within the tumor." (PMID 22630170, 2012). "Furthermore, c-KIT mRNA quantitation revealed higher levels of transcripts in normal samples compared to tumor samples (p = 0,0009)." (PMID 22839358, 2012). "Furthermore, c-KIT mRNA quantitation revealed higher transcription levels in normal samples than tumor samples." (PMID 22839358, 2012). "In general, the best therapeutic results have been obtained in tumours with KIT mutations in exons 11 (85%) and 9 (45%), although a global response rate of only 40% in inoperable tumours indicates that resection is a non-curative procedure in many cases." (PMID 23111239, 2012). "Sunitinib, a multikinase inhibitor that targets VEGFR-2, PDGFR, KIT, and FLT3, inhibited VEGFR-2 phosphorylation and VEGF-induced vascular permeability and caused tumor regression, growth arrest, or growth inhibition in tumor xenografts." (PMID 23057939, 2012). "The Korean adjuvant Phase II study referred to in this case report enrolled patients with resected primary GIST possessing KIT exon 11 mutations at high risk of recurrence (mitotic rate ≥5 mitoses/50 HPF and tumor size ≥5 cm, or mitotic rate ≥10 mitoses/50 HPF, or tumor size ≥10 cm)." (PMID 21975443, 2011). "The three cases with KIT exon 9 mutations showed the most complex CGH profiles (median of nine aberrations per tumor), followed by those with exon 11 deletions/delins (median of four aberrations per tumor)." (PMID 20470368, 2010). "Finally, we performed a separate experiment to examine the effect of twice daily, orally administered masitinib at 100 mg/kg on mice having large Δ27 KIT-expressing tumours (average tumour volume 500 mm3, 26 days post implantation of tumour cells)." (PMID 19789626, 2009). "Chronic inhibition of KIT signaling by imatinib may induce tumor cells trans-differentiation into a smooth muscle phenotype, in a subset of cases, as suggested by the ultrastructural findings and microarray studies." (PMID 19646278, 2009). "Fifteen and eleven tumours possessed mutations in KIT and PDGFRA, respectively; no mutation was found in three tumours." (PMID 19943934, 2009). "In a previous study to determine how imatinib exerts its anti-tumor effects, we demonstrated that insulin-like growth factor binding protein-3 (IGFBP3) expression is up-regulated after imatinib treatment in the imatinib-responsive GIST cell line GIST882 as well as KIT-expressing tumor samples." (PMID 19903356, 2009). "A total of 23 tumours were CD117/KIT-positive on immunohistochemistry (IHC)." (PMID 19943934, 2009). "c-KIT protein expression could be shown in 40 out of 44 (91%) tumours in at least 10% of tumour cells." (PMID 19018266, 2008).
tumor (continued). "In contrast, tumours without mutation in exon 11 had significantly lower c-KIT expression (3 out of 32 negative, 7 out of 32 (+), 7 out of 32 (++), 8 out of 32 (+++), 7 out of 32 (++++), P=0.015)." (PMID 19018266, 2008). "Interestingly, SRp55 controls the splicing profile of several tumor-associated genes, among which CD44 and KIT." (PMID 19516963, 2008). "This is supported by findings in GIST, which show KIT mutations in 75–80%, and respond significantly better to a therapy with the c-KIT inhibitor imatinib than tumours without KIT mutations." (PMID 19018266, 2008). "KIT is detectable in several human tumours, and paracrine/autocrine activation by its ligand has been suggested to be involved in numerous malignancies, including small-cell lung cancer, ovarian cancer, neuroblastoma, breast carcinoma, leukaemia, colon carcinoma and Leydig cell tumour." (PMID 16570044, 2006). "However, results of in vitro studies have since shown that sorafenib is a potent multikinase inhibitor, which also targets receptor tyrosine kinases associated with tumour angiogenesis (VEGFR-2, VEGFR-3, PDGFR-β) and tumour progression (c-KIT, FLT-3)." (PMID 16880785, 2006). "Finally, treatment of GIST patients with the KIT inhibitor Imatinib can induce tumour regression in many patients." (PMID 16570044, 2006). "FISH analysis was successful in 10 out of 12 tumours showing high KIT expression." (PMID 15583695, 2004). "Activation of human c-myc has been shown to be a common event in intermediate- and high-grade NHL and so the recurrent gain of CFA 13 observed in this study suggests that it is crucial to examine the potential involvement of c-MYC and c-KIT in canine tumour development." (PMID 14562028, 2003). "Tumours lacking variants in KIT or PDGFRA were traditionally called ‘wild-type’ (WT)." (PMID 38840030, 2025). "Together, these data support an integrated approach in which tumor size and Ki-67—interpreted alongside CD117, DOG1, and CD34, and complemented by molecular testing (KIT, PDGFRA, MMR status)—may contribute to diagnostic assessment and hypothesis generation for future risk stratification." (PMID 41465833, 2025). "GISTs are usually characterized by gain-of-function mutations in either the KIT or PDGFRA genes, leading to constitutive, ligand-independent activation of the respective receptor tyrosine kinases and downstream signaling pathways, resulting in uncontrolled tumor cell proliferation." (PMID 40590035, 2025). "Furthermore, it also alters EV composition, notably reducing KIT levels, which may influence tumor progression and metastasis." (PMID 41168571, 2025). "Moreover, PDGF plays a crucial role in the growth and metastasis of GIST, and may cooperate with c-KIT signaling to enhance tumor aggressiveness and promote oncogenic phenotypes." (PMID 40837560, 2025). "The absence of tumor growth recurrence in a model bearing a primary activating mutation of KIT in exon 11 after long-term treatment with M4205 for up to 160 days is encouraging, yet no resistance against imatinib was observed either despite being well described in patients." (PMID 40018846, 2025). "Tumor genetics, particularly mutations in the v-raf murine sarcoma viral oncogene homolog B1 (BRAF), Neuroblastoma Ras viral oncogene homolog (NRAS), and receptor tyrosine kinase proto-oncogene (c-KIT) genes, can impact how effectively T-VEC targets and destroys cancer cells." (PMID 39429342, 2024).
tumor (continued). "Notably, for patient BR360006, none of the plasma variants was detected in NGS of the matched tumor; however, by employing our tumor-agnostic approach, an ATM Q3000H mutation and a KIT C537W mutation were classified as tumor derived and evaluated for ctDNA kinetics." (PMID 37814061, 2023). "To further confirm whether the mutations of PDGFRA and KIT could promote angiogenesis, we compared the Micro-vessel density (MVD) scores which reflecting tumor angiogenesis, among the three proteomic groups, and found patients belonged to S-Im showed highest MVDs." (PMID 36720864, 2023). "Notably, a total of 10 previously reported single-nucleotide polymorphisms (SNPs) were found in this tumor in genes including MLH1 (rs769364808), FGFR3 (rs769364808), two variants (rs1873778 and rs2228230) in PDGFRA, KIT (rs55986963), APC (rs41115), and RET (rs1800861)." (PMID 37273678, 2023). "Collectively, small intestine being the predominant primary tumor site, higher KIT exon 9 mutation rate, and a greater percentage of patients with a higher ECOG PS score could have amplified the tumor severity, leading to a shorter mOS in this real-world study." (PMID 37274264, 2023). "Therefore, we applied metabolomic and integrative transcriptomic analyses of GIST tumour xenografts harvesting a KIT gene mutation, treated with imatinib and from non-treated controls." (PMID 36774883, 2023). "LEN, a multikinase inhibitor of VEGF receptors 1-3, FGF receptors 1-4, platelet-derived growth factor receptor-a, RET, and KIT, could suppress tumor angiogenesis and antitumor immunity in tumor microenvironments, which would enhance the effect of PD-1 antibodies and TACE." (PMID 36212494, 2022). "However, the median tumor volumes were 417 mL in patients with any detectable KIT mutation and 158 mL in those without (p = 0.3)." (PMID 36428589, 2022). "In addition, nintedanib increased the phosphorylation of H2AX in the primary tumour cells derived from KIT‐V559D and KIT‐K642E GIST patients, which suggested that nintedanib could induce apoptosis in part through DNA double‐strand breaks." (PMID 35194937, 2022). "Indeed, one study reported that the mutation status of c-KIT is not significantly related to Kit protein expression, is not strictly correlated with biological behaviour of the tumour and has no influence on prognosis." (PMID 36288160, 2022). "However, we observed that after a period of positive drug response, known KIT variants re-emerged in ctDNA with additional new variants that were not previously detected in tumor." (PMID 35273917, 2022). "Clinically detected GISTs may be associated with widely different tumour mitotic counts and survival outcomes despite identical KIT mutations, suggesting that the GIST phenotype is influenced by molecular factors other than the primary KIT or PDGFRA mutation." (PMID 35029030, 2022). "In addition, multiple secondary mutations have been found to appear on KIT along with the tumor progression, even in the same tumor nodule." (PMID 35174150, 2022). "However, regular panel sequencing as optimized for tumor biopsies is prone for amplifying KIT variants that are presumably not activating and likely represent background noise." (PMID 36428589, 2022). "Interestingly, the second c-KIT mutation (cases 6 and 13) and the third one (case 6) were also detected in the recurrent tumor but not in the primary lesion, indicating disease progression." (PMID 35885469, 2022). "However, dysregulation of c‐KIT can promote tumor formation and progression." (PMID 36254250, 2022). "As GIST tumors are very heterogeneous, KIT amplification might occur and most mutations are heterozygous, we are not able to conclude on the percentage of circulating tumor DNA fragments within the total amount of cfDNA." (PMID 36428589, 2022).
tumor (continued). "The difference between the 20–29 and 40 and over age groups was significant (p = 0.032), but became non-significant when adjusted for tumor type (p = 0.25) Both KIT and NRAS mutations were about twice as common among older-onset tumors than the two young-onset groups." (PMID 34819066, 2021). "Secondary resistance with tumor progression within the first 2 years of treatment remains a significant clinical problem, affecting 40% to 50% of patients under TKI treatment for metastatic GISTs, usually due to resistance mutations occurring in either KIT or PDGFRA." (PMID 34552011, 2021). "Consequently, novel TKIs may be effective against wild type c-KIT, which is expressed by the tumor-infiltrating MCs, and may be beneficial in eliminating the MCs." (PMID 34829729, 2021). "Additionally, c-KIT-targeted therapy with TKIs may ideally work against both tumor and stromal cells." (PMID 34829729, 2021). "Furthermore, the KIT expressed in the tumor of this case was examined using molecular analysis." (PMID 33827546, 2021). "However, discordant results were reported by a previous study showing that a lower tumor PD-L1 expression was correlated with a greater risk of relapse and metastasis in localized GISTs, regardless of the c-KIT mutational status." (PMID 33925671, 2021). "Interestingly, we detected a secondary KIT exon 11 (G565E) mutation in two other patients, but no tumor-specific mutation." (PMID 34552011, 2021). "Despite the strong anti-tumor effect of C-KIT inhibitors, MM patients who respond to the inhibiting agents well at the beginning will frequently experience a brief period of disease response before developing resistance to KIT inhibitors that eventually leads to progressive disease." (PMID 34350118, 2021). "After acquiring a mutation in the tyrosine kinase receptor c-KIT (CD117), the interstitial cells of Cajal (ICC), which are located in the myenteric plexus in the gastrointestinal wall and serve as a pacemaker of the gut, lose normal growth control and result in tumour formation." (PMID 33528660, 2021). "Mild to moderate nuclear atypia was significantly associated with KIT exon 11 (100%) and exon 9 mutations (100%) whereas 37.5% cases with PDGFRA exon 18 mutation and 15% of wild type GISTs showed severe atypia including plasmacytoid cells and binucleate tumour giant cells (p=0.01)." (PMID 31538651, 2020). "Notably, we confirmed that monitoring of known KIT or PDGFRA mutations in plasma with ddPCR is useful in a bigger subset of GIST patients, and that might predict tumor progression before radiological evaluation." (PMID 32024476, 2020). "To ensure that the tumor area was correctly isolated and dissected prior to nucleic acid extraction, we performed histopathological revision of the FFPE blocks of three of the four cases harboring low-allele-fraction KIT mutations (GIST_260, GIST_241 and GIST_307)." (PMID 32391261, 2020). "Additionally, tumor necrosis was more commonly seen in the KIT-9 group." (PMID 31076599, 2019). "Thus, RTK mutations, including KIT and FLT3-ITD, could activate autophagy to maintain a sufficient pool of energy substrates to sustain tumor growth and chemoresistance." (PMID 31311917, 2019). "Notably, several multi-kinase inhibitors, including dovitinib (FLT-3/c-Kit, FGFR1/3, and VEGFR) and cediranib (VEGFR, FIT1/4, and c-KIT), showed significantly high anti-tumor activities in HGSCs (P = 2.92 × 10−02 and P = 3.98 × 10−03 for dovitinib and cediranib, respectively)." (PMID 31771620, 2019).
tumor (continued). "Our results show that a subset of GISTs WT for KIT and PDGFRA, including their largest pathogenetically characterized subpopulation, i.e., the SDH-deficient ones, is significantly enriched in MGMT-methylated cases, with SDH-deficient GISTs featuring the highest prevalence of this tumor variant." (PMID 30616628, 2019). "In addition, this cluster contains two other unique mutations (D439H, I438L) not in DEPO that, based on our analysis using HotSpot3D, could also affect binding affinity and potentially tumor sensitivity to KIT combined with angiogenesis inhibitors." (PMID 30053901, 2018). "Four of the five upregulated RMGs (CTNNB1, EGFR, NRAS, and KIT) were oncogenes and 12 of the 32 downregulated RMGs were tumor suppressor genes, which was consistent with the increased expression of oncogenes and decreased expression of tumor suppressor genes in tumor development." (PMID 30107644, 2018). "Western blot analysis of the cells extracted from the tumor tissue showed that starting from 50 mg/kg dosage it could significantly affect KIT, AKT, S6 and STAT3’s phosphorylation and the effect was more clear at 100 mg/kg dosage, which is the same with Imatinib." (PMID 29340041, 2017). "However, the results of direct sequencing revealed that there was no mutation in exons 9, 11, and 13 of the KIT gene or in exon 18 of the PDGFRA gene in the tumor." (PMID 28288693, 2017). "However, the precise role of c-KIT in human tumors remains largely unknown and data from the literature present discrepancies depending on the tumor type." (PMID 28301608, 2017). "Presumably, imatinib resistance is caused by either inadequate drug concentrations, associated secondary KIT mutations or activation of signaling pathways that by pass KIT, and higher drug concentrations are thought to inhibit tumor growth in relative rather than absolute imatinib resistance." (PMID 28947997, 2017). "Besides, germline KIT-mutant subjects may suffer frequent/severe gut occlusion/hemorrage, due to the tumor numerousness." (PMID 27437068, 2016). "We now provide the first evidence that Hedgehog developmental signaling is present in the ICC lineage and is dysregulated in GIST, irrespective of KIT/PDGFRA mutations or tumor location, adding Hedgehog to the growing list of developmental signaling pathways important in GIST." (PMID 27793025, 2016). "Interestingly, the expression of both p55PIK and KIT proteins is significantly increased in tumor samples from IMA-resistance-GIST patients, suggesting that p55PIK up-regulation may be important for IMA-resistance in the clinical setting." (PMID 26587973, 2016). "Indeed, GM-CSF induces the KIT+ MDSC precursors in spleen of tumor-bearing mice." (PMID 26078490, 2015). "Moreover, activation of different two receptors, EGFR and amplified KIT (both of which could induce crizotinib resistance), also co-existed in one crizotinib-resistant tumor." (PMID 24952482, 2014). "Therefore, it is possible that in GISTs, after activation of the mutant KIT is inhibited by imatinib, other compensatory signals may become involved in maintaining tumor cell survival." (PMID 23420128, 2013). "In tumor samples gene expression analysis showed no significant variation between WT and heterozygous KIT mutated tumors, with a high inner variability in ANXA8, FBN1, GALNTL4, MFAP5 and RABEP1 expression, which was partly reduced by separating exon 9 and exon 11 mutated tumors." (PMID 23593401, 2013). "Interestingly, brain MRI images from September 2009, show that the right precentral gyrus tumor (probable KIT amplified clone) exhibited a different intensity and enhancement pattern compared to left inferior parietal tumor (KIT amplified, pre-miR-651 deletion clone)." (PMID 23029135, 2012). "Consequently, tumor cells with loss of SOCS6 may have increased activation of insulin and KIT-signaling resulting in uncontrolled growth." (PMID 22363434, 2012).